KLHL25 (kelch like family member 25)
Description:
Substrate-specific adapter of a BCR (BTB-CUL3-RBX1) E3 ubiquitin ligase complex involved in various processes, such as translation homeostasis and lipid synthesis. The BCR(KLHL25) ubiquitin ligase complex acts by mediating ubiquitination of hypophosphorylated EIF4EBP1 (4E-BP1): ubiquitination and subsequent degradation of hypophosphorylated EIF4EBP1 (4E-BP1) probably serves as a homeostatic mechanism to maintain translation and prevent eIF4E inhibition when eIF4E levels are low. The BCR(KLHL25) complex does not target EIF4EBP1 (4E-BP1) when it is hyperphosphorylated or associated with eIF4E. The BCR(KLHL25) complex also acts as a regulator of lipid synthesis by mediating ubiquitination and degradation of ACLY, thereby inhibiting lipid synthesis. BCR(KLHL25)-mediated degradation of ACLY promotes fatty acid oxidation and is required for differentiation of inducible regulatory T (iTreg) cells.
Synonyms: ENC-2; ENC2; FLJ12587
Tractability: Small molecule: it belongs to a druggable protein family. PROTAC: ubiquitination databases record sites on it; its protein half-life has been measured.
Gene: Protein-coding gene on chromosome 15 (85,759,326 to 85,794,948, reverse strand). Ensembl gene ENSG00000183655.
Subcellular location (Human Protein Atlas): Cytosol; Nucleoplasm
Pathways (Reactome):
Immune System: Antigen processing: Ubiquitination & Proteasome degradation
Metabolism of proteins: Neddylation
Gene Ontology:
Molecular function: protein binding; ubiquitin-like ligase-substrate adaptor activity
Biological process: negative regulation of fatty acid biosynthetic process; positive regulation of CD4-positive, CD25-positive, alpha-beta regulatory T cell differentiation; positive regulation of fatty acid oxidation; protein ubiquitination; regulation of translational initiation; ubiquitin-dependent protein catabolic process; proteasome-mediated ubiquitin-dependent protein catabolic process; protein catabolic process
Cellular component: Cul3-RING ubiquitin ligase complex; cytoplasm; cytosol
Genetic constraint (gnomAD): Loss-of-function variants: 41 observed, 30.67 expected, observed/expected ratio (o/e) 1.34, 90% interval 1.04 to 1.73. The upper end of that interval is the gene's LOEUF score, 1.73, which puts it in group 6 of 6, group 1 being the genes least tolerant of losing a copy. Missense variants: 971 observed, 856.21 expected, observed/expected ratio (o/e) 1.13, 90% interval 1.08 to 1.2. Synonymous variants: 399 observed, 369.9 expected, observed/expected ratio (o/e) 1.08, 90% interval 0.99 to 1.17.
Homologues: Orthologues: chimpanzee KLHL25 (99% identical), macaque KLHL25 (99% identical), dog KLHL25 (98% identical), mouse Klhl25 (95% identical), rat Klhl25 (95% identical), guinea pig KLHL25 (94% identical), rabbit KLHL25 (90% identical), zebrafish enc2 (85% identical), tropical clawed frog klhl25 (85% identical), pig KLHL25 (65% identical), Drosophila melanogaster gprs (14% identical). Paralogues in human: ENC1 (75% identical), BTBD17 (13% identical).
Diseases named in the same sentence as KLHL25 in open-access papers:
KLHL25 is named in the same sentence as 8 diseases in open-access papers, as found by Europe PMC text mining. Sharing a sentence is not in itself a finding about the gene and the disease. The quoted sentences say what the papers report.
lung carcinoma (3 papers, 2020 to 2025). "The E3 ligase CUL3 interacts with its adaptor protein KLHL25 to degrade ACLY in cells, thereby inhibiting lipid synthesis and growth of lung cancer cells." (PMID 39944823, 2025). "A Kelch-like family member, KLHL25, bound cul3 to ubiquitinate and degrade ACLY, thereby inhibit inhibits tumor progression of lung cancer cells." (PMID 33109073, 2020). "Among the genes belonging to this family, KLHL25, KLHL3, and KLHL6 were found to be up-regulated by the fluorinated chalcone; curiously, these genes have been described to inhibit cell migration and invasiveness in lung carcinoma, diffuse large B-cell lymphoma, and chronic lymphocytic leukemia." (PMID 40332279, 2025).
KLHL25 also shares sentences with these, for which no sentence is quoted: chronic lymphocytic leukemia (1 paper); colitis (1); diffuse large B-cell lymphoma (1); gastric cancer (1); immune diseases (1); non-alcoholic fatty liver disease (1); tumor (1).